NPTX1 (neuronal pentraxin 1)
Diseases named in the same sentence as NPTX1 in open-access papers (continued):
Sharing a sentence is not in itself a finding about the gene and the disease.
tumor (16 papers, 2008 to 2025). "NPTX1 has been implicated in inhibiting tumor growth across multiple types of cancer, acting through distinct signaling pathways." (PMID 37958599, 2023). "However, the present study is the first to show that NPTX1 expression level correlates with clinicopathological factors (tumor size and metastasis) in HCC and is associated with survival time in HCC patients." (PMID 31113871, 2019). "A deeper analysis revealed upregulation of genes involved in tumor suppression (Clca2, Spink5, Igfbp6, Nptx1, Bex4, Gadd45g, Yipf5), immune regulation (IL6ra, Ccl6, Cd81, Cd244a, Cd151, and Gata4), apoptosis, and pyroptosis (Ddit3, Rgs6, and Gsdmsc2/3/4)." (PMID 39946195, 2025). "Increasing the activity of NPTX1 is tumor suppressive, and therefore, the downregulation of lncRNA SLC26A4-AS1 causes loss of tumor suppression and oncogenesis." (PMID 40564171, 2025). "Herein, we provide the first report that NPTX1 is down-regulated in HCC and that NPTX1 expression is correlated with tumor size and metastasis." (PMID 31113871, 2019). "We observed that the expression of NPTX1 was decreased significantly in HCC and was associated with tumor size and metastasis in patients." (PMID 31113871, 2019). "Three (NNAT, SST and NPTX1) of the 7 hypermethylated gene promoters have been reported to be methylated in tumours previously." (PMID 19025626, 2008). "Notably, numerous important genes, including novel biomarkers such as circSETD3 and NPTX1, are still engaged in tumor invasion and metastasis." (PMID 35890278, 2022). "Moreover, the results of q-RT PCR showed that CTSV, RGS4, SYT13 and NPTX1 were highly expressed in tumor tissues compared with adjacent tumor tissues, while SLC25A15, ENTPD2 and CA8 were low expressed." (PMID 36684237, 2022). "Collectively, our findings suggest that NPTX1 inhibits tumor growth and promotes apoptosis in vivo." (PMID 31113871, 2019). "Thus, it would be of particular interest to examine whether knockdown or inhibition of MFAP4, NPTX1, and/or HMGA2 suppresses tumor development of BAP1-deficient MMe cells." (PMID 37479714, 2023). "Furthermore, we found by Kaplan–Meier analysis that patients whose tumors showed low NPTX1 expression levels had significantly shorter overall survival and tumor-free survival times than did patients whose tumors showed high NPTX1 expression levels (P=0.0335 and 0.0368, respectively)." (PMID 31113871, 2019). "In-depth analysis of the DEGs that exhibited significant changes in K562 cells treated with WIP2W showed an elevation of tumor suppressor genes, including OSCP1, and genes related to cell apoptosis such as FXYD6, NPTX1, and GPR142." (PMID 37765274, 2023). "NPTX1 expression was enhanced by hsa_circ_0070269 in HCC cells via sponging miR-182, which prevented aggressive tumor behavior." (PMID 36672755, 2022). "Also, we identified NCAM1, CNTN1, SCG2, CADM1, IL-8, NPTX1, and APOD as PSCB in the tumor secretome." (PMID 31455042, 2019). "Although down-regulated expression of NPTX1 occurs in diverse tumor types, the function and molecular mechanisms are not fully understood." (PMID 31113871, 2019). "Neural lineage markers, such as NCAM1 (early) and NPTX1 (neuronal), were highly expressed in 143BNSC tumours, whereas genes involved in cancer proliferation, including EYA2, VCAN, HMGA1 and TXNIP, were highly expressed in 143BGBM tumours." (PMID 27551510, 2016).
cancer (14 papers, 2008 to 2025). A tumor composed of atypical neoplastic, often pleomorphic cells that invade other tissues. "NPTX1 has been reported to be intimately associated with a wide range of cancers and its aberrant activation was closely related to tumorigenesis and progress." (PMID 32090639, 2020). "NPTX1 is a member of the pentraxin family and a major risk factor for nervous system disorders, and its downregulation expression has been reported in many cancers." (PMID 32869505, 2020). "It was reported that the NPTX1 regulated the development and growth of cancers mainly through activation of the PI3K/AKT pathway." (PMID 32090639, 2020). "Four genes are hypermethylated in all 9 tested cancers, while for SST (7 of 9 carcinomas), HTRA3 (1 of 9 carcinomas) and NPTX1 (5 of 10 carcinomas) a fraction of the tested carcinomas is hypermethylated." (PMID 19025626, 2008). "Additionally, miR193a-CM upregulated NPTX1, a member of pentraxin family, which inhibits proliferation and promotes apoptosis in cancer cells." (PMID 36230929, 2022). "All these findings indicated that epigenetic regulation may be an important reason why NPTX1 shows low expression in various cancers, and ultimately contributes to the poor prognosis." (PMID 31113871, 2019). "Our transcriptomic data align with existing studies that have identified genes like NPTX1, TRIM31, and CD82/KAI1 as potential therapeutic targets in various cancers." (PMID 37958599, 2023). "Seven of these predicted proteins (NCAM1, CNTN1, SCG2, CADM1, IL-8, NPTX1, and APOD) were identified in five databases (SignalP 4.1, SecretomeP 2.0, Vesiclepedia, Human Cancer Secretome, and Plasma Proteome), giving support to their relevance in NSCLC." (PMID 31455042, 2019). "NPTX1 inhibits the level of Cyclin A2 in HCC, implicating an anti-cancer role of NPTX1 in cancer progression." (PMID 31113871, 2019).
neurological diseases (3 papers, 2020 to 2024). "The surface abundance of one of the members of the family, NPTX1, governs AMPA receptor clustering and neurotransmission strength and its dysfunction is associated with several neurological diseases." (PMID 39466808, 2024). "Another study representing the first transcriptome sequencing study proposed the association of seven genes (CTSS, SERPINA1, NPTX1, PTX3, CHI3L1, SERPINA3, and MX1) as “the missing link” to explain the correlation between HHV-6A infection and neurological diseases." (PMID 35683449, 2022).
adenocarcinoma (1 paper, 2021). A common cancer characterized by the presence of malignant glandular cells. "In total, four novel genes, including NPTX1, PCSK1, ASXL3, and TRIM9, were all significantly upregulated in NEPC compared with the adenocarcinoma samples, and these genes were all associated with the neuroactive ligand receptor interaction pathway." (PMID 34646089, 2021).
neurodegenerative disease (1 paper, 2020). A disorder of the central nervous system characterized by gradual and progressive loss of neural tissue and neurologic function. "As this protein likely constitutes a protein associated with both neuronal degradation and synaptic loss, future work will be needed to determine the specificity of NPTX1 for AD versus other neurodegenerative diseases." (PMID 32518535, 2020).
renal disease (1 paper, 2022). "This calls for further exploration to fully elucidate the role of NPTX1 both in the AhR pathway and in renal disease." (PMID 35216489, 2022). "In the adenine mouse model of CKD, increased levels of Nptx1 in the aorta were also observed, suggesting that there may be an upregulation of Nptx1 during renal disease." (PMID 35216489, 2022). "On the other hand, if NPTX1 continuously increased in vivo during the progression of renal disease, as observed in the aorta of CKD mice, this might indicate that the impact of NPTX1 can be deleterious." (PMID 35216489, 2022).
NPTX1 also shares sentences with these, for which no sentence is quoted: cervical cancer (3 papers); gastric cancer (3); colorectal cancer (2); renal carcinoma (2); alcohol dependence (1); amyotrophic lateral sclerosis (1); cognitive decline (1); cryptococcosis (1); depression (1); endometrial cancer (1); fibroid tumor (1); fragile X syndrome (1); fungal infection (1); glioblastoma (1); hearing loss (1); Hyperglycemia (1); idiopathic pulmonary fibrosis (1); Intellectual disability (1); liver cancer (1); memory impairment (1); mood disorder (1); ovarian carcinoma (1); squamous cell carcinoma (1); stomach cancer (1); thyroid cancer (1).